MSRB1 (methionine sulfoxide reductase B1)
Description:
Methionine-sulfoxide reductase that specifically reduces methionine (R)-sulfoxide back to methionine. While in many cases, methionine oxidation is the result of random oxidation following oxidative stress, methionine oxidation is also a post-translational modification that takes place on specific residue. Acts as a regulator of actin assembly by reducing methionine (R)-sulfoxide mediated by MICALs (MICAL1, MICAL2 or MICAL3) on actin, thereby promoting filament repolymerization. Plays a role in innate immunity by reducing oxidized actin, leading to actin repolymerization in macrophages.
Synonyms: SelX; SEPX1; HSPC270; SelR; SepR; SELENOX; SELENOR
Tractability: PROTAC: UniProt records ubiquitination sites on it.
Gene: Protein-coding gene on chromosome 16 (1,938,229 to 1,943,199, reverse strand). Ensembl gene ENSG00000198736.
Subcellular location: Cytoplasm; Nucleus; Cytoplasm, cytoskeleton
Subcellular location (Human Protein Atlas): Nucleoplasm
Pathways (Reactome):
Metabolism of proteins: Protein repair
Gene Ontology:
Molecular function: protein binding; actin binding; L-methionine (R)-S-oxide reductase activity; peptide-methionine (R)-S-oxide reductase activity; zinc ion binding
Biological process: actin filament polymerization; innate immune response; protein repair
Cellular component: nucleoplasm; actin cytoskeleton; cytoplasm; cytosol; nucleus; cytoskeleton
Genetic constraint (gnomAD): Loss-of-function variants: 13 observed, 14.38 expected, observed/expected ratio (o/e) 0.9, 90% interval 0.59 to 1.43. The upper end of that interval is the gene's LOEUF score, 1.43, which puts it in group 5 of 6, group 1 being the genes least tolerant of losing a copy. Missense variants: 174 observed, 155.52 expected, observed/expected ratio (o/e) 1.12, 90% interval 0.99 to 1.27. Synonymous variants: 68 observed, 65.11 expected, observed/expected ratio (o/e) 1.04, 90% interval 0.86 to 1.28.
Homologues: Orthologues: guinea pig MSRB1 (91% identical), pig MSRB1 (91% identical), rat Msrb1 (91% identical), dog MSRB1 (91% identical), mouse Msrb1 (91% identical), rabbit MSRB1 (89% identical), zebrafish msrb1b (66% identical), tropical clawed frog msrb1 (61% identical), macaque MSRB1 (50% identical), Drosophila melanogaster MsrA (11% identical), Caenorhabditis elegans msra-1 (9% identical). Paralogues in human: MSRB3 (34% identical), MSRB2 (34% identical), MSRA (16% identical).
Diseases named in the same sentence as MSRB1 in open-access papers:
MSRB1 is named in the same sentence as 37 diseases in open-access papers, as found by Europe PMC text mining. Sharing a sentence is not in itself a finding about the gene and the disease. The quoted sentences say what the papers report.
Obesity (3 papers, 2018 to 2023). Accumulation of substantial excess body fat. "It has also been demonstrated that obesity upregulates the hepatic expressions of MsrB1, SELENON, SELENOP, and SELENOW, as well as GPx4 in diabetic patients by 33–35% compared to non-obese subjects." (PMID 37895024, 2023). "It has been demonstrated that obesity up-regulates hepatic expressions of MSRB1, SELENON, -P, and -W, as well as GPX4 in diabetic patients by 33–50%, as compared to non-obese examinees." (PMID 32344656, 2020). "Particularly, diet-induced obesity in HFD-fed (45% calories from fat) reduced both MsrA and MsrB (predominantly Msrb1) activities, as well as their protein abundances in VAT, but not SAT." (PMID 32344656, 2020). "Experiments studying diet-induced obesity in HFD-fed subjects, with 45% calories from fat, reduced both MsrA and MsrB (predominantly MsrB1, also known as SELENOR) activities and also their protein abundance in VAT (visceral adipose tissue) but not in SAT (subcutaneous adipose tissue)." (PMID 37895024, 2023).
breast carcinoma (2 papers, 2007 to 2020). "Since Sp1 is ubiquitously expressed, these sites, while necessary, are not sufficient to explain the patterns of gene expression of MsrB1 in various human breast cancer cells." (PMID 17519015, 2007). "In fact, a lower level of MsrB1 protein was detected in crude extracts obtained from MDA-MB231 cells versus MCF7 cells, suggesting a different MsrB1 transcriptional regulation in these human breast cancer cell lines." (PMID 17519015, 2007). "In this study, we investigated the transcriptional regulation of the MsrB1 gene in human breast cancer cells." (PMID 17519015, 2007). "The human MCF7 and MDA-MB231 cells were chosen as breast cancer cell models for the analysis of the MsrB1 promoter activity." (PMID 17519015, 2007). "In the present study, we showed evidence indicating a differential pattern of MsrB1 expression in breast cancer cell lines." (PMID 17519015, 2007). "The MsrB1 promoter PCR fragment was obtained from both breast cancer cell lines." (PMID 17519015, 2007). "In contrast, we show in this report, using ChIP experiments, that Sp1 binds the MsrB1 promoter region in both high-expressing MCF7 and low-expressing MDA-MB231 breast cancer cells." (PMID 17519015, 2007). "The aim of this study was to investigate the regulation of MsrB1 selenoprotein levels through transcriptional regulation of the MsrB1 gene in MDA-MB231 and MCF-7 breast carcinoma cell lines." (PMID 17519015, 2007). "High levels of MsrB1 transcript, protein and promoter activity were detected in low metastatic MCF7 human breast cancer cells." (PMID 17519015, 2007). "High levels of MSRB1 were previously found in hepatocellular carcinoma, and correlated with the MAPK pathway and epithelial-mesenchymal transition (EMT), and in low metastatic MCF7 human breast cancer cells." (PMID 32933107, 2020).
hepatocellular carcinoma (2 papers, 2018 to 2020). A malignant tumor that arises from hepatocytes. "However, few studies have examined the role of MsrB1 in human hepatocellular carcinoma (HCC)." (PMID 29861830, 2018).
Sepsis (2 papers, 2011 to 2023). Sepsis is defined as life-threatening organ dysfunction caused by a dysregulated host response to infection. "In conclusion, we used bioinformatics methods to screen three key macrophage-related genes, SGK1, DYSF and MSRB1, which have a good diagnostic effect on sepsis-induced ARDS." (PMID 37336980, 2023).
skin inflammation (2 papers, 2017 to 2024). "We subjected WT and MsrB1 KO mice to an acute dermatitis model that involved topical treatment of the left auricle with the chemical irritant TPA and the right auricle with acetone (vehicle)." (PMID 28698597, 2017). "Meanwhile, MsrB1 KO mice presented with greater severity of TPA-induced skin inflammation with significantly increased skin thicknesses." (PMID 28698597, 2017). "Consequently, this result proves that A06, B03, and B05, identified as MsrB1 inhibitors, suppress the expression of IL-10 and IL-1rn and, thereby, promote skin inflammation." (PMID 39594490, 2024).
diabetes (1 paper, 2021). "Similar to GPX1, MSRB1 has been shown to act in the Se-mediated regulation of energy metabolism and diabetes risk." (PMID 34679693, 2021).
hearing loss (1 paper, 2025). "Among the four paralogs (MSRA, MSRB1, MSRB2, MSRB3), so far, only MSRA and MSRB3 have been associated with hearing loss." (PMID 40827380, 2025).
hypertrophy (1 paper, 2021). Hypertrophy is the increase in the volume of an organ or tissue due to the enlargement of its component cells. "Cardiac hypertrophy in response to triiodothyronine or isoproterenol treatment was found to upregulate the expression of MsrB1, GPX3, GPx4, and Txnrd1, leading to the speculation that their increased expression may mitigate cardiac damage following induction of hypertrophy." (PMID 34579115, 2021).
ischemia (1 paper, 2023). A hypoperfusion of the BLOOD through an organ or tissue caused by a PATHOLOGIC CONSTRICTION or obstruction of its BLOOD VESSELS, or an absence of BLOOD CIRCULATION. "A recent study has found that betaine could increase the expression of MetO reductases b1 (Msrb1) and b2 (Msrb2) to exert a neuroprotective effect in ischemia/reperfusion injury‐induced brain damage." (PMID 37183324, 2023).
liver cancer (1 paper, 2018). An epithelial or non-epithelial malignant neoplasm that arises from the liver. "The results of the IHC analysis of the relationship between MsrB1 expression levels and clinicopathological characteristics showed that MsrB1 expression was correlated with tumor size (P = 0.04), age (P = 0.028), liver cirrhosis (P = 0.04), and Barcelona Clinic Liver Cancer (BCLC) stage (P = 0.03)." (PMID 29861830, 2018).
liver disease (1 paper, 2018). "We found that MsrB1 mRNA expression was upregulated in 5 of the 6 HCC tissue samples compared with 8 of the 9 tumor-free liver disease tissue samples." (PMID 29861830, 2018). "To detect MsrB1 expression in HCC tissues and paratumor tissues, we analyzed MsrB1 mRNA levels in tissue samples from 9 patients with tumor-free liver disease and 6 patients with HCC using RT-PCR." (PMID 29861830, 2018).
malaria (1 paper, 2014). Malaria is a serious and sometimes fatal disease caused by a parasite that commonly infects a certain type of mosquito which feeds on humans. "In the severe malaria groups, intracellular proteins (TIPIN, MSRB1), components of glucose metabolism (ADSSL1, DNPEP1) and an inflammatory protein (DAPK1) had increased levels, further confirming observations made above with the ‘targeted array’." (PMID 24743550, 2014).
cancer (9 papers, 2007 to 2024). A tumor composed of atypical neoplastic, often pleomorphic cells that invade other tissues. "Indeed, MsrB1 has been shown to be associated with certain pathological conditions, including the incidence and development of several cancers, modulation of the immune response, regulation of brain function, aging, etc.." (PMID 39594490, 2024). "In addition, MsrB1/SelR has been implicated in the regulation of cell proliferation and apoptosis, as well as in the development of various diseases, such as cancer, neurodegenerative disorders, and cardiovascular disease." (PMID 38202719, 2023). "Most studies with cancer cells generally report the methylation of selenoproteins like glutathione peroxidase 1 and 3, methionine sulfoxide reductase B1 and selenium binding protein 1 in the promoter region." (PMID 32722369, 2020). "Looking at the top 5 coding mutations, for example, we noted that corresponding genes (FES, TNFSF15, MSRB1, HRAS, and SLC1A7) have all been experimentally implicated in cancer as drivers." (PMID 32859160, 2020). "The results of our analysis showed that MsrB1 DNA copy number in the cancer tissue samples was twice as high as that in the paratumor tissue samples." (PMID 29861830, 2018). "In the present study, we reported evidence indicating a differential MsrB1 expression in two human cancer cell lines derived from the same tissue and we elucidated the mechanisms responsible for the MsrB1 gene expression." (PMID 17519015, 2007). "Since selenium appears to protect against certain cancers and pathogens, it may be worthwhile to study the role that MsrB1 plays in the immunological processes that are involved in cancer and pathogen challenge." (PMID 33092166, 2020). "We found different MsrB1 expression levels in cancer cell lines derived from the same tissue." (PMID 17519015, 2007). "However, there is still a need for more inhibitors, particularly for MsrB1, given the potential therapeutic benefits of enhancing inflammation in certain cases, such as chronic infections, vaccine adjuvants, cancer immunotherapy, and immunocompromised patients." (PMID 39594490, 2024).
tumor (3 papers, 2018 to 2025). "After 8 weeks, the sizes of the HCC tumors in the sh-MsrB1 group were significantly smaller than those in the sh-NC group, indicating that MsrB1 knockdown inhibited tumor growth in a xenograft tumorigenicity model." (PMID 29861830, 2018). "Compared with patients with low expression, patients with high MsrB1 expression had worse overall survival and tumor-free survival." (PMID 29861830, 2018). "In vivo, MsrB1 knockdown effectively inhibited tumor growth." (PMID 29861830, 2018). "Additionally, if MsrB1 could also exert such a direct role in vivo, then MsrB1 may play an important role in regulating neuronal synaptic formation, immune cell migration, tumor cell proliferation, and other pathological processes." (PMID 33806413, 2021). "However, only a few studies have focused on the function of MsrB1 in tumor biology." (PMID 29861830, 2018). "In this study, MsrB1-interferenced HCC cells showed decreased proliferation and metastasis, suggesting that this factor can be a biological target for tumor therapy." (PMID 29861830, 2018). "MsrB1 knockdown in HCC cells resulted in proliferation and metastasis downregulation, suggesting that this factor may be suitable as a biological target for tumor therapy." (PMID 29861830, 2018).
neurodegenerative disease (2 papers, 2021 to 2023). A disorder of the central nervous system characterized by gradual and progressive loss of neural tissue and neurologic function. "Therefore, further exploration of the physiological role of MsrB1 will be helpful for understanding the function of selenium in the central nervous system and the treatment of neurodegenerative diseases." (PMID 33806413, 2021).
kidney diseases (1 paper, 2023). "Based on the known functions of the DKD candidate marker genes, it appears that many associate with kidney diseases, and our stress score genes, particularly GPX3, HRSP12, MSRA, MSRB1, and CRYAB, protect the cell and/or cellular proteins during stress." (PMID 37216114, 2023).
MSRB1 also shares sentences with these, for which no sentence is quoted: infection (6 papers); rectal cancer (4); colon cancer (3); Alzheimer disease (2); infective endocarditis (2); mastitis (2); pneumonia (2); abscess (1); Ataxia (1); atopic dermatitis (1); bacteremia (1); cardiovascular disease (1); dermatitis (1); hyperglycaemia (1); influenza (1); liver cirrhosis (1); pyrexia (1); scalded skin syndrome (1); schizophrenia (1); skin abscess (1); skin infection (1).